COL4A1 (collagen type IV alpha 1 chain)
Diseases named in the same sentence as COL4A1 in open-access papers (continued):
Sharing a sentence is not in itself a finding about the gene and the disease.
colon cancer (3 papers, 2015 to 2022). "In addition, it has been reported that COL4A1 and COL4A2 were associated with high risk of relapse in colon cancer." (PMID 32704448, 2020). "The Western blot assay indicated that FLNC, COL6A3, COL4A1 and SPON2 were abundantly expressed in the colonic fibroblasts instead of the colon cancer epithelial cells." (PMID 26338966, 2015). "We chose COL4A1, COL6A3, spondin-2 (SPON2) and FLNC for further analysis for their high abundance (peptide count), high “fold change” and less chances being identified in colon cancer cell lines." (PMID 26338966, 2015).
familial porencephaly (3 papers, 2014 to 2021). An instance of porencephaly that is caused by an inherited modification of the individual's genome. "In 2005, COL4A1 mutations were identified to segregate with human familial porencephaly." (PMID 34551193, 2021). "Mutations in COL4A1 were first associated with cerebral microangiopathy and familial porencephaly." (PMID 25124159, 2014).
fibrosis (3 papers, 2022 to 2024). the formation of excess fibrous connective tissue in an organ or tissue in a reparative or reactive process. "In vascular ageing, we only observed an association of this trajectory with fibrosis, likely owing to the four collagen genes in this trajectory (Col4a1, 5a3, 6a3, 15a1)." (PMID 36718802, 2023).
gastric tumor (3 papers, 2022 to 2025). "In contrast, the high frequency of COL4A1 alterations observed in our analysis appears less widely reported in previous STAD studies, indicating that COL4A1 may represent a comparatively under recognized mutational contributor to gastric tumor progression." (PMID 41291892, 2025). "Moreover, several immunotherapies based clinical analyses have reported that stromal rich gastric tumors exhibit reduced responses to immune checkpoint inhibitors, which supports our observation that COL4A1 and THBS2 correlate with markers of an immune suppressive microenvironment." (PMID 41291892, 2025).
Hyperglycemia (3 papers, 2011 to 2022). An increased concentration of glucose in the blood. "Db/db mice with pressure ulcers showed an impairment in the molecular regulation of hypoxia-related genes (Hif1a, Flt1, and Kdr), while extracellular matrix encoding genes (Itgb3, Timp1, Fn1, Col4a1) were upregulated by hyperglycemia and lesions." (PMID 35386010, 2022). "One of the more important findings of this work was that PVT1 effects on expression of FN1, COL4A1, and PAI-1 may be mediated independently of TGFB1, a well-known profibrotic factor which promotes tissue fibrosis by upregulating genes encoding ECM proteins in response to hyperglycemia." (PMID 21526116, 2011).
Infertility (3 papers, 2019 to 2022). "COL4A1 downregulation in infertile human endometrium reduces endometrial epithelial cell adhesive capacity, which implied COL4A1 expression can inhibit primary tumor segregation and result in metastasis." (PMID 32565804, 2020). "Once we established that miR-29c negatively regulates COL4A1 mRNA in the early secretory infertile endometrium, we aimed to see if knockdown of COL4A1 in vitro would reduce HEEC adhesion, similarly to miR-29c overexpression." (PMID 31201347, 2019). "COL4A1 localises to the luminal and glandular epithelium basement membranes of early and mid-secretory phase fertile and infertile endometrium." (PMID 31201347, 2019). "COL4A1 was immunolocalised to the luminal and glandular epithelial basement membranes in early and mid-secretory phase fertile and infertile endometrium for the first time." (PMID 31201347, 2019). "COL4A1 protein localised to the luminal and glandular epithelium basement membranes in early and mid-secretory phase endometrium from fertile and infertile women." (PMID 31201347, 2019). "Targeting COL4A1 or miR-29c in vivo may be useful in facilitating implantation in women and furthering our understanding of human infertility, however further studies are required to establish an in vivo role." (PMID 31201347, 2019). "To determine if increased miR-29c in vivo may correlate with COL4A1 protein levels we immunolocalised COL4A1 in the early and mid-secretory phase infertile endometrium, which had not previously been reported." (PMID 31201347, 2019). "Our data demonstrate that alterations in miR-29c or COL4A1 levels alter primary HEEC adhesive capacity and suggest that the interactions between miR-29c and COL4A1 may impair HEEC adhesive capacity by disrupting basement membrane integrity, contributing to implantation failure and infertility." (PMID 31201347, 2019).
leiomyoma (3 papers, 2008 to 2019). A well-circumscribed benign smooth muscle neoplasm characterized by the presence of spindle cells with cigar-shaped nuclei, interlacing fascicles, and a whorled pattern. "First, we examined the DNA methylation status of the IRS1 and COL4A1 using combined bisulfite restriction analysis in Case1, Case2, Case3 and additional 7 paired samples of leiomyoma and matched myometrium." (PMID 23818951, 2013). "IRS1 is also reported to be involved in the upregulation of collagen genes, including COL4A1, COL4A2 and COL6A3, suggesting that IRS1 possibly contributes to the leiomyoma nodule formation by upregulating the gene expression of COL4A1, COL4A2, and COL6A3." (PMID 23818951, 2013). "At higher concentrations of ATRA, the relative COL4A1 gene expression between leiomyoma and myometrial cells remained comparable." (PMID 18248652, 2008). "Taken together, ATRA exposure reduced COL1A1 and COL4A1 mRNA expression in leiomyoma cells, approaching expression patterns comparable to myometrial cells." (PMID 18248652, 2008). "The mRNA expression was increased for collagen genes COL1A1 (2·72 ± 0·55-fold; P < 0·05) and COL4A1 (2·95 ± 0·37-fold; P < 0·05) in leiomyoma cells as compared to myometrial cells prior to treatment." (PMID 18248652, 2008). "COL4A1 template also demonstrated a down-regulation of gene expression in treated leiomyoma cells as compared to treated myometrial cells with greatest change at 10−8m ATRA (0·89 + 0·12; P < 0·05)." (PMID 18248652, 2008). "The genes associated with “cancer process” contained potentially novel or relevant candidate genes for leiomyoma formation such as IRS1, COL4A1, COL4A2, COL6A3, and GSTM5." (PMID 23818951, 2013). "Collagen-related genes such as COL4A1 and COL4A2 have been previously reported to be upregulated in leiomyomas." (PMID 23818951, 2013).
microcephaly (3 papers, 2018 to 2025). A congenital or acquired developmental disorder in which the circumference of the head is smaller than normal for the person's age and sex. "Interestingly, we found several differentially expressed genes following infection with ZIKV Uganda, including COL4A1, MIR17HG, TUBA1A, SLC2A1 and STAMBP, which are associated with microcephaly according to the comparative toxicogenomics database." (PMID 33121145, 2020).
multi-infarct dementia (3 papers, 2021 to 2023). A common form of dementia caused by multiple cortical or subcortical cerebral infarctions. "Genetic analysis showed a c.*32G > A mutation in the 3′ untranslated region of COL4A1, which was identical to the mutation described in patients with multi-infarct dementia of Swedish type." (PMID 34415564, 2022). "A 3′UTR mutation of COL4A1 caused hereditary multi‐infarct dementia in a Swedish family." (PMID 34551193, 2021). "Our findings suggest that the novel c.*34G > T mutation appears to have the same functional consequences as the previously reported COL4A1 gene mutations in patients with PADMAL and multi-infarct dementia of Swedish type." (PMID 34415564, 2022). "Recently, mutations causing overproduction of COL4A1 have been identified in patients with pontine autosomal dominant microangiopathy with leukoencephalopathy (PADMAL) and multi-infarct dementia of Swedish type." (PMID 34415564, 2022). "Three different heterozygous mutations, including c.*32G > T, c.*32G > T, and c.*35C > A, in the 3′ untranslated region of COL4A1, were identified in patients with PADMAL while a c.*32G > A mutation was found in patients with multi-infarct dementia of Swedish type." (PMID 34415564, 2022).
anaemia (2 papers, 2016 to 2020). "Col4a1 mutant mice display reduced blood volume and haematocrit levels but normal plasma volume, and recently, anaemia has been described in individuals with a COL4A1 mutation." (PMID 26839400, 2016). "Further studies are required to clarify how COL4A1 mutations are involved in anemia." (PMID 33298904, 2020).
asthma (2 papers, 2022 to 2025). "As such, we investigated how asthma-associated ECM proteins fibronectin (FN1), tenascin-C (TNC) and collagen 4α1 (COL4A1) are altered at a transcriptional and protein level in the absence of RPS4Y1." (PMID 40649992, 2025).
basal cell carcinoma (2 papers, 2023 to 2025). A carcinoma involving the basal cells. "Three key genes, VCAN, COL4A1 and COL5A2, may be involved in multiple activated signalling pathways in basal cell carcinoma, and they are co-enriched in extracellular space, extracellular region and endoplasmic reticulum lumen, extracellular matrix." (PMID 40386063, 2025).
bleeding (2 papers, 2024 to 2025). "Emerging evidence points to genetic factors, such as mutations in COL4A1 and COL4A2 genes, as relevant to neonatal intracranial bleeding." (PMID 40126707, 2025).
CADASIL syndrome (2 papers, 2023). "For instance, a novel COL4A1 gene variant associated with CADASIL syndrome was recently found to be associated with GBM." (PMID 37749605, 2023).
cancers of the brain (2 papers, 2013 to 2021). "Since type IV collagens are major components of the basement membrane and their overexpression is linked to cancers of the brain, stomach and liver, expression and/or modulation of COL4A1/A2 genes might be part of the molecular changes associated with DCIS." (PMID 34238275, 2021).
cardiac hypertrophy (2 papers, 2023 to 2024). "Animal models have shown that FGF2 is important for the manifestation of cardiac hypertrophy, whereas COL4A1 is involved in extracellular matrix organization, which has been linked with atherogenesis." (PMID 38576084, 2024). "Using qPCR, we found that the expression of ANP, BNP, COL1A1, and COL4A1 mRNA in cardiomyocytes following COX6A2 knockdown was significantly increased compared with that of the WT cells, suggesting that the cardiomyocytes developed toward cardiac hypertrophy and fibrosis." (PMID 38072986, 2023).
cerebral cavernous malformation (2 papers, 2022 to 2024). A disorder characterized by malformations in the structure of the capillaries in the brain. "The disorders we identified were Moyamoya disease (MMD), COL4A1, COL4A2 pathogenic variant, Ehlers–Danlos syndrome (E-D), neurofibromatosis type 1 (Nf1), sickle cell disease (SCD), cerebral cavernous malformations (CCM), hereditary hemorrhagic telangiectasia (HHT) and Marfan syndrome." (PMID 38790247, 2024).
cobblestone lissencephaly (2 papers, 2011 to 2012). "Recent findings that mutations in COL4A1 cause an ocular/muscular/cortical developmental disorder in mice and WWS in humans without affecting the level of glycosylated α-dystroglycan further supports the heterogeneous etiology of cobblestone lissencephaly." (PMID 22235340, 2012). "Together, these findings demonstrate that Col4a1+/Δex40 mice have abnormal neuronal localization typical of cobblestone lissencephaly observed in MEB/WWS patients and suggest that these congenital defects are secondary to breaches in the pial basement membrane." (PMID 21625620, 2011).
colon adenocarcinoma (2 papers, 2022 to 2025). "COL4A1 was involved in diabetic tubulointerstitial injury and COL5A2 participated in the progression of uterine fibroids and colon adenocarcinoma, although their functions were not fully understood for GDM development." (PMID 36544488, 2022).
Corneal opacity (2 papers, 2014 to 2024). A reduction of corneal clarity. "Consistent with a protective effect of Tgfbr2 heterozygosity, fewer eyes having corneal opacity were excluded in the Col4a1+/G1344D;Tgfbr2+/– group than in the Col4a1+/G1344D;Tgfbr2+/flox group." (PMID 38717426, 2024).
cyst (2 papers, 2014 to 2025). A sac-like closed membranous structure that may be empty or contain fluid or amorphous material. "While sequence analysis of patient IV:21, who has a large porencephalic cyst, excluded COL4A1 mutations, it identified a base pair change in exon 28 of COL4A2 that is predicted to substitute a glycine residue of a Gly-X-Y repeat for aspartic acid (G702D)." (PMID 24001601, 2014). "Similarly, pathogenic variants in COL4A1 further emphasize the connection between basement membrane integrity and cyst formation, affecting the α1α1α2(IV) network predominantly in Bowman’s capsule and tubules." (PMID 40565535, 2025).
diabetic cardiomyopathy (2 papers, 2014 to 2025). Diabetic cardiomyopathy is a disorder of the heart muscle in people with diabetes. "We and others have previously shown the presence of focal fibrosis in diabetic cardiomyopathy and that there is increased expression of TGF-β1 signalling accompanied by enhanced COL4A1 and FN1 production." (PMID 24428157, 2014).
Encephalopathy (2 papers, 2020 to 2024). Encephalopathy is a term that means brain disease, damage, or malfunction. "COL4A1 mutations are close mimickers of static encephalopathy with characteristic neuroimaging findings." (PMID 39310498, 2024). "Our findings provide evidence that COL4A1-related encephalopathy can be inherited in an autosomal recessive manner, which is important for counseling, prognosis, and treatment." (PMID 32042920, 2020).
endothelial dysfunction (2 papers, 2024). In vascular diseases, endothelial dysfunction is a systemic pathological state of the endothelium (the inner lining of blood vessels) and can be broadly defined as an imbalance between vasodilating and vasoconstricting substances produced by (or acting on) the endothelium. "To investigate if Col4a1 glycine mutations cause endothelial dysfunction via reduced collagen IV levels, we investigated vascular function in 3-month-old Col4a2+/em2Wtsi mice." (PMID 39216230, 2024). "Here we show collagen IV is a regulator of endothelial cell-mediated vasodilation and that in CSVD Col4a1 missense mutations cause endothelial dysfunction with dysregulated EDH vasodilation through reduced extracellular collagen IV levels, and biomechanical and structural vascular defects." (PMID 39216230, 2024).
Epileptic encephalopathy (2 papers, 2019 to 2021). A condition in which epileptiform abnormalities are believed to contribute to the progressive disturbance in cerebral function. "Firstly, a pathogenic COL4A1 variant (NM_001845.5: c.2494G>A: p.G832R) was identified in P204, a male with choreoathetoid quadriplegia, cystic porencephaly and epileptic encephalopathy." (PMID 31700678, 2019).
familial hemiplegic migraine type 1 (2 papers, 2020 to 2025). "This study presents novel evidence linking hemiplegic migraine (HM) to rare variants in genes previously implicated in cerebral SVD, including LRP1, COL4A1, and TGFBR2." (PMID 40869943, 2025).
gastric adenocarcinoma (2 papers, 2020 to 2022). "We identified THBS1, FN1, CALM1, COL4A1, CTGF, and IGFBP5 as potential inflammation-related targets for the treatment of gastric adenocarcinoma." (PMID 32801999, 2020).
glomerulopathy (2 papers, 2016 to 2021). "By contrast, 40-day-old animals present with BM defects and glomerulopathy, but much lower levels of chronic pathogenic ER stress compared with 3-month-old Col4a1+/Raw mice." (PMID 26839400, 2016). "Col4a1 mutations cause a glomerulopathy and tubulopathy with medullary atrophy, leading to proteinuria and diabetes insipidus because of a defect in the ability to concentrate urine." (PMID 26839400, 2016).
Hypermetropia (2 papers, 2018 to 2020). An abnormality of refraction characterized by the ability to see objects in the distance clearly, while objects nearby appear blurry. "We describe here the phenotype of a likely pathogenic gene variant, p.Gly743Val, which is responsible for a missense mutation in the COL4A1 gene exon 30 in a three generation family with severe hypermetropia and highly penetrant porencephaly in the absence of systemic manifestations." (PMID 33013618, 2020).
hypertrophic cardiomyopathy (2 papers, 2022 to 2025). A condition in which the myocardium is hypertrophied without an obvious cause. "During the rest phase (CT30 and CT34), ECM-receptor interaction (e.g., Tnxb, Col4a1, and Col6a1) was the most enriched pathway among genes downregulated in WT KPC mice, while hypertrophic cardiomyopathy (e.g., Des, Tnnc1, and Myl3) was the most enriched pathway among upregulated genes." (PMID 40349340, 2025).
invasive ductal breast carcinoma (2 papers, 2017 to 2024). The most common type of invasive breast carcinoma, accounting for approximately 70% of breast carcinomas. "based on the bioinformatics analysis, a series of the experiments were performed to verify the results obtained from the data mining, and indicated that overexpressed COL4A1 gene promote the proliferation of the invasive ductal carcinomas cells SKBR3." (PMID 28938546, 2017). "Additionally, experimental results shows that the COL4A1 gene, one of identified genes, played important roles in both of proliferation and colony formation in Invasive ductal carcinoma." (PMID 28938546, 2017).
keratoconus (2 papers, 2011 to 2022). A degenerative, structural disorder of the eye, characterized by a cone-shaped protrusion of the cornea. "Results from expression arrays have shown an expression of COL4A1 in transplant-quality human donor corneas and a downregulation of COL4A1 in keratoconus corneas." (PMID 21527998, 2011).
kidney failure (2 papers, 2016 to 2026). An acute or chronic condition that is characterized by the inability of the kidneys to adequately filter the blood. "Furthermore, patients who identified with PKD2 and COL4A1 mutations developed kidney failure earlier than those with monogenic disorders." (PMID 41557100, 2026).
liver cirrhosis (2 papers, 2020 to 2023). "Apart from this, COL4A1 and COL4A2 were in the top 5% over-expression gene rank of liver cirrhosis and HCC in both datasets." (PMID 31905170, 2020). "Both COL4A1 and COL4A2 were found in the top 5% of the over-expression-gene-rank of liver cirrhosis and the top 3% of HCC." (PMID 31905170, 2020). "The mRNA expression levels of COL4A1 and COL4A2 were significantly upregulated in patients with liver cirrhosis and HCC tissues in two datasets." (PMID 31905170, 2020).
low grade glioma (2 papers, 2022 to 2025). A grade I or grade II glioma arising from the central nervous system. "Elevated COL4A1 expression was correlated with poorer survival of patients with low-grade glioma (LGG)." (PMID 40351420, 2025).
muscular dystrophy (2 papers, 2019 to 2022). Muscular dystrophy (MD) refers to a group of more than 30 genetic diseases characterized by progressive weakness and degeneration of the skeletal muscles that control movement. "Analysis of skeletal muscle from COL4A1 mutant animals identified a muscular dystrophy phenotype with myofiber atrophy, centronucleation, focal inflammatory infiltrates, and fibrosis." (PMID 35866615, 2022). "Morphological characteristics of muscular dystrophy have also been demonstrated Col4a1 mutant mice." (PMID 31623094, 2019). "Our results indicated that muscular dystrophy may also be present in col4a1 mutant Drosophila." (PMID 31623094, 2019).
Myocardial fibrosis (2 papers, 2019 to 2022). "The expression of different genes related to myocardial fibrosis was assessed in the rat hearts, revealing that at the 3rd week TiO2-NPs instillation the expression of different collagen isoform genes (namely COL1A2, COL3A1, COL4A1) were definitively upregulated in treated animals compared to CTRL." (PMID 31234877, 2019).